MRPL48 (mitochondrial ribosomal protein L48)
Synonyms: L48mt; MRP-L48; CGI-118; HSPC290; mL48
Tractability: Small molecule: a structure with a bound ligand is known. PROTAC: ubiquitination databases record sites on it; its protein half-life has been measured.
Gene: Protein-coding gene on chromosome 11 (73,787,872 to 73,865,133, forward strand). Ensembl gene ENSG00000175581.
Subcellular location: Mitochondrion
Subcellular location (Human Protein Atlas): Mitochondria
Pathways (Reactome):
Metabolism of proteins: Mitochondrial ribosome-associated quality control; Mitochondrial translation elongation; Mitochondrial translation initiation; Mitochondrial translation termination
Gene Ontology:
Molecular function: protein binding
Biological process: mitochondrial translation
Cellular component: mitochondrial large ribosomal subunit; mitochondrial ribosome; mitochondrion; mitochondrial inner membrane
Genetic constraint (gnomAD): Loss-of-function variants: 15 observed, 27.95 expected, observed/expected ratio (o/e) 0.54, 90% interval 0.36 to 0.83. The upper end of that interval is the gene's LOEUF score, 0.83, which puts it in group 3 of 6, group 1 being the genes least tolerant of losing a copy. Missense variants: 206 observed, 220.87 expected, observed/expected ratio (o/e) 0.93, 90% interval 0.83 to 1.05. Synonymous variants: 93 observed, 80.44 expected, observed/expected ratio (o/e) 1.16, 90% interval 0.98 to 1.37.
Homologues: Orthologues: chimpanzee MRPL48 (99% identical), macaque MRPL48 (97% identical), dog MRPL48 (87% identical), guinea pig MRPL48 (86% identical), pig MRPL48 (83% identical), mouse Mrpl48 (81% identical), rat Mrpl48 (80% identical), tropical clawed frog mrpl48 (51% identical), zebrafish mrpl48 (48% identical), Drosophila melanogaster mRpL48 (25% identical), Caenorhabditis elegans mrpl-48 (23% identical).
Diseases named in the same sentence as MRPL48 in open-access papers:
MRPL48 is named in the same sentence as 12 diseases in open-access papers, as found by Europe PMC text mining. Sharing a sentence is not in itself a finding about the gene and the disease. The quoted sentences say what the papers report.
hepatocellular carcinoma (2 papers, 2023 to 2025). A malignant tumor that arises from hepatocytes. "Bioinformatic analysis and in vitro model studies show that knockdown of MRPL48 reduces the proliferation, migration, and invasion of hepatocellular carcinoma cells." (PMID 40371222, 2025). "This suggests that MRPL48 may play a significant role in the development of hepatocellular carcinoma, with its high expression potentially promoting the malignant behavior of hepatocellular carcinoma cells." (PMID 40371222, 2025).
cholangiocarcinoma (1 paper, 2023). A carcinoma that arises from the intrahepatic biliary tree (intrahepatic cholangiocarcinoma) or from the junction, or adjacent to the junction, of the right and left hepatic ducts (hilar cholangiocarcinoma). "The expression of MRPL48 was significantly higher in tumor tissues than in adjacent normal tissues for almost all tumor types, including breast invasive carcinomas (BRCA) and cholangiocarcinomas (CHOLs)." (PMID 38093387, 2023).
colorectal cancer (1 paper, 2023). A primary or metastatic malignant neoplasm that affects the colon or rectum. "The expression of MRPL48 has been reported to be elevated in several types of cancer, including osteosarcomas and colorectal cancers." (PMID 38093387, 2023). "Studies have shown that MRPL48 is of predictive value for the occurrence and prognosis of osteosarcoma, as well as promotes the growth of colorectal cancer cells." (PMID 38093387, 2023). "Studies have shown that MRPL48 can predict osteosarcoma incidence and prognosis, as well as promotes colorectal cancer progression." (PMID 38093387, 2023). "HuTT reported that knockdown of MRPL48 expression using the CRISPR-Cas 9 technique could significantly increase the sensitivity of colorectal cancer cells to cetuximab." (PMID 38093387, 2023).
emphysema (1 paper, 2022). "We also detected low levels of the mitoribosome structural protein MRPL48 in ATII cells in emphysema." (PMID 35884802, 2022). "Our results indicate a reduced expression of the MRPL48 subunit accompanying the downregulation of 16S rRNA in ATII cells in emphysema, which agrees with this study." (PMID 35884802, 2022). "Moreover, we did not detect any significant changes in MRPS27 and MRPL48 levels using lung tissue obtained from nonsmokers, smokers, and emphysema patients by RT-PCR and Western blotting." (PMID 35884802, 2022).
Non-alcoholic steatohepatitis (1 paper, 2023). "Finally, further analysis of MRPL48 mRNA expression between HBV, HCV, and NASH (Non-alcoholic steatohepatitis)-related HCC and control samples was conducted in the GEO database, and we observed remarkably elevated MRPL48 levels in HBV- and NASH-associated HCC samples, but not in HCVs." (PMID 38093387, 2023).
osteosarcoma (1 paper, 2023). A usually aggressive malignant bone-forming mesenchymal neoplasm, predominantly affecting adolescents and young adults. "Zhang used the WGC-NA algorithm and LASSO, PPI, and MOCDE methods to verify that high MRPL48 expression is associated with the poor prognosis of osteosarcoma patients." (PMID 38093387, 2023).
retinoblastoma (1 paper, 2023). A malignant tumor that originates in the nuclear layer of the retina. "GSEA showed that the expression of the MRPL48 was correlated with Resolution of Sister Chromatid Cohesion, Mitotic Prometaphase, Retinoblastoma Gene in Cancer, RHO Gtpases Activate Formins, Mitotic Metaphase and Anaphase, and Cell Cycle Checkpoints." (PMID 38093387, 2023).
schizophrenia (1 paper, 2025). A major psychotic disorder characterized by abnormalities in the perception or expression of reality. "Notably, MRPL48 displays a female-specific paternal expression bias in the medial preoptic area and is differentially expressed in patients with schizophrenia compared to healthy controls." (PMID 40414938, 2025).
cancer (2 papers, 2023 to 2025). A tumor composed of atypical neoplastic, often pleomorphic cells that invade other tissues. "Further studies are required to elucidate the mechanisms by which MRPL48 contributes to cancer development and progression." (PMID 39859078, 2025). "MRPL48 transcriptional levels in various human cancers and in their corresponding normal tissues were investigated using TCGA and GTEx datasets." (PMID 38093387, 2023). "The results indicated that higher levels of MRPL48 mRNA tended to be expressed in tissues obtained from HCC patients with advanced cancer stages (p < 0.01), and the highest mRNA levels of MRPL48 were predominantly found in patients at stages T2 and T3." (PMID 38093387, 2023). "As the first step, we determined MRPL48 transcription levels in different types of cancer based on independent datasets of different sources (TCGA and GTEx, respectively)." (PMID 38093387, 2023). "Through the use of independent datasets from different sources, we examined the expression levels of MRPL48 in different types of cancer." (PMID 38093387, 2023). "However, there is limited research and understanding regarding the role of MRPL48 in cancer, and its role in cancer is not well understood." (PMID 39859078, 2025). "MRPL48 is upregulated in many types of cancer, including HCC, breast cancer, and gastric cancer, a phenomenon which may be due to the hypomethylation of its promoter." (PMID 39859078, 2025).
neurological disorders (1 paper, 2025). "In addition, MRPL48 has been implicated in the development of nervous and endocrine system, with its dysregulation linked to hereditary, metabolic, and neurological disorders." (PMID 40414938, 2025).
tumor (1 paper, 2023). "Although MRPL48 has been increasingly recognized as a new tumor biomarker, transcriptional analysis of MRPL48 in human HCC has not been extensively conducted." (PMID 38093387, 2023). "There was a significant decrease in MRPL48 promoter methylation of TCGA HCC tumor tissues, compared with normal tissues adjacent to cancerous tissue in UALCAN (p < 0.001)." (PMID 38093387, 2023). "We analyzed the DEGs in tumors with high and low expression levels of MRPL48 to investigate potential mechanisms of MRPL48-mediated tumor progression." (PMID 38093387, 2023). "Furthermore, we examined the association between MRPL48 expression and clinical characteristics of patients with HCC and determined that MRPL48 expression was correlated with T classification, pathological tumor grade, AFP level, and vascular invasion." (PMID 38093387, 2023). "We studied the correlation between MRPL48 expression and the clinical and pathological features of HCC patients, including the T classification, the pathological tumor grade, the AFP level, and the vascular invasion of tumors." (PMID 38093387, 2023).
MRPL48 also shares sentences with these, for which no sentence is quoted: infection (1 paper).